SEMA3C (semaphorin 3C)
Diseases named in the same sentence as SEMA3C in open-access papers (continued):
Sharing a sentence is not in itself a finding about the gene and the disease.
infection (1 paper, 2023). The state of being infected such as from the introduction of a foreign agent such as serum, vaccine, antigenic substance or organism. "The right panel shows CoV2 infection downregulating SEMA3C expression." (PMID 38203569, 2023). "With less SEMA3C, more NRP1 receptors are available for CoV2 binding, thus increasing the infection of other NRP1-presenting cells, including respiratory and olfactory epithelium." (PMID 38203569, 2023).
neurodegenerative disease (1 paper, 2025). A disorder of the central nervous system characterized by gradual and progressive loss of neural tissue and neurologic function. "Among the affected genes were APOE (apolipoprotein E), SEMA3C (semaphorin 3C), and NTNG1 (netrin G1), which have established roles in energy regulation and neurodegenerative disease." (PMID 41009961, 2025).
retinopathy (1 paper, 2015). "Sema3C administration strongly inhibited the formation of pathological pre-retinal vascular tufts during oxygen-induced retinopathy." (PMID 26194913, 2015). "The local injection of a single dose of recombinant Sema3C protein into the vitreous body in a mouse model of oxygen-induced retinopathy did not change the size of the vaso-obliterative zone within the retina." (PMID 26194913, 2015).
SEMA3C also shares sentences with these, for which no sentence is quoted: ovarian carcinoma (3 papers); prostate tumors (3); brain tumor (2); colorectal cancer (2); epilepsy (2); fibrosis (2); Abdominal obesity (1); Alzheimer disease (1); benign prostatic hyperplasia (1); brain cancer (1); CHARGE syndrome (1); colon cancer (1); gastric tumor (1); intracranial aneurysms (1); melanoma (1); neurological disease (1); oral lichen planus (1); osteoarthritis (1); Parkinson disease (1); renal carcinoma (1); renal clear cell carcinoma (1); respiratory failure (1); Rolandic epilepsy (1); septic shock (1); steatosis (1); Tetralogy of Fallot (1); triple-negative breast carcinoma (1); type 2 diabetes (1); ventricular septal defect (1).